RBMX (RNA binding motif protein X-linked)
Diseases named in the same sentence as RBMX in open-access papers (continued):
Sharing a sentence is not in itself a finding about the gene and the disease.
HIV-1 infection (2 papers, 2020 to 2022). The type species of lentivirus and the etiologic agent of acquired immunodeficiency syndrome (AIDS). "In this study, we report another hnRNP member, RBMX, as a novel viral restriction factor that suppresses HIV-1 infection of CD4+ T cells by modulating HIV-1 5′-LTR-driven transcription." (PMID 32317327, 2020). "In this study, the deletion of RRM in RBMX reduced its binding to HIV-1 proviral DNA but maintained its ability to inhibit HIV-1 infection, indicating that an indirect binding of RBMX with HIV-1 proviral DNA is mediating the inhibitory role." (PMID 32317327, 2020). "RBMX knockdown resulted in a 15- to 47-fold enhancement of HIV-1 infection based on the results from five independent experiments." (PMID 32317327, 2020). "The additional knockdown of SUV39H1 further reduced RBMX-mediated enhancement for HIV-1 infection from 6.1-fold to 2.6-fold, representing a 57% suppression." (PMID 32317327, 2020). "In this study, we found that RBMX suppresses HIV-1 infection by modulating HIV-1 5′-LTR-driven viral transcription." (PMID 32317327, 2020). "Conversely, overexpression of RBMX in Jurkat T cells inhibited HIV-1 infection." (PMID 32317327, 2020). "RBMX knockdown significantly promoted HIV-1 infection and production." (PMID 32317327, 2020). "RBMX binds with and maintains H3K9me3 modification to suppress HIV-1 infection." (PMID 32317327, 2020). "Taken together, these data demonstrate the modulative role of RBMX on HIV-1 infection." (PMID 32317327, 2020). "Similar results were obtained by using HEK293T cells with knockdown of RBMX, in which there was enhancement of HIV-1 infection and gag mRNA production but no change in gag DNA level." (PMID 32317327, 2020). "The ΔRRM mutant was capable of inhibiting HIV-1 infection but unable to bind HIV-1 proviral DNA at the 1108 nucleic acid site, indicating that direct binding of RBMX with HIV-1 proviral DNA is not responsible for mediating the inhibitory role." (PMID 32317327, 2020).
lymph node metastases (2 papers, 2017 to 2021). "A correlation analysis of clinicopathological features revealed that a low RBMX level was positively related to lymph node metastasis status (pN, P = 0.029) and high-grade clinical stage (P = 0.009)." (PMID 33564070, 2021).
osteosarcoma (2 papers, 2025). A usually aggressive malignant bone-forming mesenchymal neoplasm, predominantly affecting adolescents and young adults. "The analysis of clinical samples and experimental data revealed that RBMX is significantly overexpressed in osteosarcoma tissues and is closely associated with poor patient prognosis." (PMID 40941025, 2025). "Following infection with RBMX-knockout lentivirus, the RBMX expression in mouse osteosarcoma cells was significantly decreased compared with the empty group." (PMID 40941025, 2025). "Several m6A genes, including METTL3, RBM15, IGF2BP3, and RNA-binding motif protein X (RBMX), were significantly upregulated in OS cell lines and OS tissues compared to osteoblast and non-osteosarcoma tissues." (PMID 40510136, 2025). "Subcutaneous tumor models were constructed by RBMX gene knockout mouse osteosarcoma cell lines, and the key cell groups regulated by them were identified by single-cell transcriptome sequencing analysis." (PMID 40941025, 2025). "To understand the effects of RBMX on the progression of osteosarcoma, we analyzed the single-cell transcriptome of human osteosarcoma tissue (GSE162454)." (PMID 40941025, 2025). "The incorporation rate of EdU was significantly decreased in the RBMX knockout cells, as compared to the empty control, suggesting that downregulation of RBMX inhibited osteosarcoma cell proliferation." (PMID 40941025, 2025). "In vitro cell experiments showed that knockout of RBMX significantly inhibited the proliferation of mouse osteosarcoma cells." (PMID 40941025, 2025). "The results of this study revealed that RBMX is an important regulatory factor of the osteosarcoma microenvironment." (PMID 40941025, 2025). "This study systematically revealed, for the first time, the key role of RBMX in the regulation of the immune microenvironment of osteosarcoma." (PMID 40941025, 2025). "In this study, the expression of RBMX in osteosarcoma was identified using the TARGET database and clinical samples." (PMID 40941025, 2025). "To further understand the effects of RBMX knockout on the osteosarcoma immune microenvironment, we separated the tumor tissue and isolated single cells for transcriptome sequencing." (PMID 40941025, 2025). "Elucidating RBMX-mediated immunoregulatory pathways could provide critical insights into osteosarcoma immune evasion and inform novel immunotherapeutic approaches." (PMID 40941025, 2025). "Transcriptome sequencing analysis revealed that RBMX was highly expressed in osteosarcoma tissues." (PMID 40941025, 2025). "This study found that RBMX is highly expressed in human osteosarcoma." (PMID 40941025, 2025). "However, there are currently few relevant research reports on the exploration of RBMX in osteosarcoma." (PMID 40941025, 2025). "However, the mechanism by which RBMX specifically regulates the TME state of osteosarcoma remained unclear." (PMID 40941025, 2025). "Secondly, this study found that RBMX is highly expressed in osteosarcoma and may promote tumor progression by inhibiting the activity of CD8+T cells." (PMID 40941025, 2025). "The high expression of RBMX may mediate the immunosuppressive microenvironment of human osteosarcoma." (PMID 40941025, 2025). "Thus, the potential involvement of RBMX in osteosarcoma progression through TME modulation requires further investigation, particularly regarding its underlying molecular mechanisms." (PMID 40941025, 2025). "Targeting RBMX could allow for alteration of the osteosarcoma microenvironment, thus inhibiting its progression, and offer novel targets and strategies for precise immunotherapy." (PMID 40941025, 2025). "However, research on RBMX in osteosarcoma is still unclear, and there are few related reports on the immune microenvironment." (PMID 40941025, 2025).
osteosarcoma (continued). "Finally, the mechanism by which RBMX regulates the immune microenvironment state was explored through cell communication analysis and PCR experiments, providing a scientific basis for the treatment and prognosis of osteosarcoma." (PMID 40941025, 2025). "In addition, osteosarcoma patients with a high expression of RBMX had a poorer prognosis." (PMID 40941025, 2025). "Through investigating N6-Methyladenosine modification regulatory factors in the osteosarcoma TME, this study found that the expression of RBMX was significantly negatively correlated with the infiltration level of CD8+T cells." (PMID 40941025, 2025). "Further experiments revealed that RBMX regulates the expression of H2-K1 and THBS1, driving the depletion of CD8+T cells in osteosarcoma through cell communication." (PMID 40941025, 2025). "The impact of RBMX knockout on CD8+T cells within the osteosarcoma microenvironment is not yet understood." (PMID 40941025, 2025). "Firstly, in this study on the impact of RBMX expression on prognosis in osteosarcoma, due to the lack of corresponding clinical information, it is impossible to accurately reflect whether RBMX is an independent prognostic factor for osteosarcoma." (PMID 40941025, 2025).
papillary thyroid carcinoma (2 papers, 2020 to 2023). "Mutations in RBMX were recently reported in papillary thyroid carcinoma cells resistant to vemurafenib, and knock-down of wild-type RBMX caused an increase of p-AKT protein level in naïve cancer cells." (PMID 31936151, 2020). "In the absence of RBMX gene, some thyroid cancers (papillary thyroid carcinoma) obtain vemurafenib resistance." (PMID 37756323, 2023).
viral infection (2 papers, 2023). "The role of MAK16 and H3Y2 in viral infection is unclear, while RBMX, which encodes X-ed RNA binding motif proteins, responds to SARS-CoV-2 entry via viral RNA-host protein interactions." (PMID 36690780, 2023). "Some reports showed RBMX implicated in viral infection and cancer." (PMID 37194014, 2023).
adenosquamous carcinoma (1 paper, 2024). A carcinoma composed of malignant glandular cells and malignant squamous cells. "Mutations of RBMX found in patients with adenosquamous carcinoma suppressed the expression of RBMX, while tobacco-induced mutations of RBMX can increase the incidence of cancer among smokers." (PMID 38214653, 2024).
basal cell carcinoma (1 paper, 2023). A carcinoma involving the basal cells. "Through OCLR algorithm, it can be seen that mRNAsi, EREG-MRNASI value has significant difference between the two clusters (p < 0.05), suggesting that FMR1, LRPPRC, RBMX, YTHDC2 and IGF2BP1 may affect CRC by regulating the pathway of basal cell carcinoma." (PMID 37194014, 2023).
cervical squamous cell carcinoma (1 paper, 2024). A squamous cell carcinoma arising from the cervical epithelium. "Overall survival (OS) analysis revealed that RBMX was a protective factor in patients suffering from cervical squamous cell carcinoma and endocervical adenocarcinoma (CESC), KIRC, rectum adenocarcinoma (READ), THYM, UCS, and uveal melanoma (UVM)." (PMID 38214653, 2024).
chronic lymphocytic leukemia (1 paper, 2025). "RBMX regulates the mTOR signaling pathway by stabilizing CPT1A and participates in lipid metabolism and proliferation in chronic lymphocytic leukemia, promoting the progression of the disease." (PMID 40941025, 2025).
colorectal cancer (1 paper, 2023). A primary or metastatic malignant neoplasm that affects the colon or rectum. "The signature might provide five candidate targets (RBMX, FMR1, IGF2BP1, LRPPRC, YTHDC2) associated with specific clinical features, prognosis and improvement in immunotherapy for patients with colorectal cancer." (PMID 37194014, 2023). "To clarify the role of RBMX, FMR1, IGF2BP1, LRPPRC and YTHDC2, we analyzed the mRNA expression patterns in human colorectal cancer specimens." (PMID 37194014, 2023).
epilepsy (1 paper, 2022). A brain disorder characterized by episodes of abnormally increased neuronal discharge resulting in transient episodes of sensory or motor neurological dysfunction, or psychic dysfunction. "The random forest (RF) model was applied to the screening, and seven m6A regulators (HNRNPC, WATP, RBM15, YTHDC1, YTHDC2, CBLL1, and RBMX) were selected as the candidate genes for predicting the risk of epilepsy." (PMID 36468034, 2022). "Firstly, we analyzed the expression of 17 m6A-related genes extracted from a public dataset and found that seven of them (HNRNPC, WTAP, RBM15, YTHDC1, YTHDC2, CBLL1, and RBMX) were differentially expressed between patients with epilepsy and healthy individuals." (PMID 36468034, 2022). "We found a positive correlation between the expression of HNRNPC, RBMX, and RBM15 in patients with epilepsy." (PMID 36468034, 2022).
glioblastoma (1 paper, 2024). The most malignant astrocytic tumor (WHO grade IV). "Subsequently, we verified the presence of aberrant RBMX protein levels in clinical liver hepatocellular carcinoma (LIHC), glioblastoma (GBM), and cholangiocarcinoma (CHOL) samples compared with adjacent tissues." (PMID 38214653, 2024).
glioma (1 paper, 2024). A benign or malignant brain and spinal cord tumor that arises from glial cells (astrocytes, oligodendrocytes, ependymal cells). "Analysis of the glioma microenvironment indicated high expression of RBMX in malignant cells and monocytes/macrophages." (PMID 38214653, 2024). "Next, we analyzed the distribution of RBMX expression in the glioma microenvironment using the data of GSE131928, which includes 7,930 cells from 28 patients with glioma." (PMID 38214653, 2024).
Gustavson syndrome (1 paper, 2023). "In conclusion, we present a novel in-frame deletion in RBMX segregating with Gustavson syndrome, leading to disturbed RNA polymerase II transcription, and potentially reduced SH3 binding." (PMID 37277488, 2023).
head and neck squamous cell carcinoma (1 paper, 2023). A squamous cell carcinoma that arises from any of the following anatomic sites: lip and oral cavity, nasal cavity, paranasal sinuses, pharynx, larynx, and salivary glands. "It is reported that RBMX and HNRNPC can predict the prognosis of head and neck squamous cell carcinoma and are related to immune infiltration." (PMID 37194014, 2023).
intellectual disabilities (1 paper, 2023). "The results indicate that disruption of different protein domains affects the severity of RBMX-associated intellectual disabilities." (PMID 37277488, 2023).
major depression (1 paper, 2021). "Here, we detected a 27bp tandem repeat deletion in the intergenic region between RBMX and the GPR101 genes that segregated together in all the BD type I diagnosed P101 family members, as well as in one affected with major depression." (PMID 34914762, 2021).
pancreatic adenocarcinoma (1 paper, 2024). "The results showed remarkable positive relationships between RBMX and immune regulators in HNSC, KICH, LIHC, and pancreatic adenocarcinoma, as well as negative relationships in GBM, SARC, and testicular germ cell tumors (TGCT)." (PMID 38214653, 2024).
polyneuropathies (1 paper, 2024). "Among these, PNPLA6 and RBMX are described in polyneuropathies and neurological disorders." (PMID 39409151, 2024).
prostatic intraepithelial neoplasia (1 paper, 2022). "The expressions of RBMX were gradually increased from prostatic intraepithelial neoplasia to hormone-naïve prostate cancer compared with normal samples." (PMID 35211628, 2022).
Sepsis (1 paper, 2023). Sepsis is defined as life-threatening organ dysfunction caused by a dysregulated host response to infection. "In this predictive nomogram, the expression levels of FTO, HNRNPC, RBMX, YTHDC1, LRPPRC, and RBM15B were negatively associated with the risk score of patients with sepsis and were regarded as protective factors in sepsis." (PMID 36781867, 2023).
Shashi X-linked mental retardation syndrome (1 paper, 2021). "Mental retardation, X-linked, syndromic 11 (MRXS11; also known as Shashi X-linked mental retardation syndrome; OMIM 300238) is associated with a hemizygous mutation in the gene encoding the RBP RBMX (also known as hnRNP G)." (PMID 34564083, 2021).
stomach adenocarcinoma (1 paper, 2024). "Moreover, the data obtained from the disease-free interval (DFI) analysis suggested that RBMX is a protective factor in BRCA, brain lower grade glioma (LGG), READ, stomach adenocarcinoma (STAD), and THCA." (PMID 38214653, 2024).
synovial sarcoma (1 paper, 2024). "Among them, METTL3, YTHDC1, YTHDC2, RBMX, and ELAVL1 were significantly upregulated in synovial sarcoma tissue." (PMID 38549939, 2024).
X-linked syndromic mental retardation-11 (1 paper, 2021). "Mutations in RBMX have also been associated with X-linked syndromic mental retardation-11(MRXS11; OMIM 300238)." (PMID 34914762, 2021).
tumor (46 papers, 2017 to 2025). "RBMX binds to miR-19b-3p and promotes distant metastasis of lung cancer and it also drives the M2 polarization of tumor-associated macrophages (TAMs), thereby accelerating colorectal cancer progression." (PMID 40941025, 2025). "Abnormal expression of RBMX is associated with immune regulation, prognosis, the tumor microenvironment, immune cell infiltration, MSI, and TMB." (PMID 38214653, 2024). "Moreover, further experiments should be conducted to identify the specific mechanism underlying the regulatory effect of RBMX on tumor progression, particularly in terms of regulating the proliferation, migration, and invasion of cancer cells." (PMID 38214653, 2024). "Similarly, our analysis showed that RBMX was highly expressed in HCC tumor tissues and negatively associated with the expression of lncRNA AC115619.1." (PMID 37614318, 2023). "For example, the RBMX gene, as a key regulator, is closely linked to important cancer drivers with evidence that it may act as a tumour suppressor and may help to protect the integrity of the genome from damage." (PMID 36077923, 2022). "Interestingly, we have shown that activation of AKT in resistant cell lines might be connected with acquired mutations in a gene encoding RBMX, an RNA-binding protein protecting cells against DNA damage and acting as a tumor suppressor." (PMID 31936151, 2020). "Further analysis revealed that knockout of RBMX significantly increased the proportion of CD8+T cells in immune cells of subcutaneous tumor tissues." (PMID 40941025, 2025). "RBMX can affect the invasion, metastasis, and regulation of the immune microenvironment of tumor cells." (PMID 40941025, 2025). "Most regulators, such as METTL3, YTHDF1, IGF2BP3, and RBMX, were upregulated in tumor tissues, while METTL14 and ZC3H13 were downregulated." (PMID 40916616, 2025). "The results showed that in the LM8 and K7M2 cell lines, knockout of RBMX significantly increased the proportion of CD45+ cells in subcutaneous tumor tissues." (PMID 40941025, 2025). "Collectively, these results indicate that RBMX knockout in tumor cells boosts CD8+T cell activity by promoting H2-K1 and inhibiting THBS-1 expression." (PMID 40941025, 2025). "Related studies have found that the RNA-binding motif protein, X-linked (RBMX), plays a regulatory role in modulating the biological characteristics of the tumor microenvironment (TME)." (PMID 40941025, 2025). "By constructing a mouse subcutaneous tumor model, we determined that knockout of RBMX significantly inhibited the growth of subcutaneous implant tumors, and the mice had a longer survival time." (PMID 40941025, 2025). "Our findings emphasized the correlations between RBMX and MDSC in the tumor microenvironment, as well as the role of RBMX as a predictor of response to immunotherapy." (PMID 38214653, 2024). "The heatmap illustrated that the immune cells (particularly dendritic cells [DC] and T prolif) accounted for most RBMX expression in the majority of tumor types." (PMID 38214653, 2024). "Initially, we extracted data from TCGA and GTEx databases to detect differences in the expression levels of RBMX between tumor and normal tissues." (PMID 38214653, 2024). "To further analyze the distribution of RBMX-expressing cells in tumor microenvironments, we applied the single-cell analysis of RBMX using the Tumor Immune Single-cell Hub (TISCH) webtool." (PMID 38214653, 2024). "Subsequently, we performed progression-free interval (PFI) analysis to evaluate the role of RBMX in tumor death, recurrence, and metastasis." (PMID 38214653, 2024). "Typical pictures of IHC staining revealed that RBMX was localized in the cell nucleus and the expression of RBMX in tumor tissues was higher than that in adjacent normal liver tissues, which was negatively correlated with the AC115619.1 expression in HCC." (PMID 37614318, 2023).